TBCA (tubulin folding cofactor A)
Description:
Tubulin-folding protein; involved in the early step of the tubulin folding pathway.
Tractability: PROTAC: ubiquitination databases record sites on it; its protein half-life has been measured.
Gene: Protein-coding gene on chromosome 5 (77,691,166 to 77,868,780, reverse strand). Ensembl gene ENSG00000171530.
Subcellular location: Cytoplasm, cytoskeleton
Subcellular location (Human Protein Atlas): Microtubules; Nucleoli
Pathways (Reactome):
Metabolism of proteins: Post-chaperonin tubulin folding pathway
Gene Ontology:
Molecular function: protein binding; RNA binding; protein-folding chaperone binding; tubulin binding; beta-tubulin binding
Biological process: post-chaperonin tubulin folding pathway; protein folding; tubulin complex assembly
Cellular component: microtubule cytoskeleton; cytoplasm; cytoskeleton
Genetic constraint (gnomAD): Loss-of-function variants: 4 observed, 8.55 expected, observed/expected ratio (o/e) 0.47, 90% interval 0.23 to 1.07. That is too few expected variants to judge how well the gene tolerates losing a copy. Missense variants: 72 observed, 85.76 expected, observed/expected ratio (o/e) 0.84, 90% interval 0.69 to 1.02. Synonymous variants: 24 observed, 27.67 expected, observed/expected ratio (o/e) 0.87, 90% interval 0.63 to 1.22.
Homologues: Orthologues: chimpanzee TBCA (100% identical), macaque TBCA (95% identical), guinea pig TBCA (94% identical), pig TBCA (94% identical), dog TBCA (93% identical), mouse Tbca (93% identical), tropical clawed frog tbca (81% identical), rat Tbca (80% identical), zebrafish tbca (75% identical), Drosophila melanogaster Tbca (43% identical), Caenorhabditis elegans tbca-1 (35% identical).
Diseases named in the same sentence as TBCA in open-access papers:
TBCA is named in the same sentence as 18 diseases in open-access papers, as found by Europe PMC text mining. Sharing a sentence is not in itself a finding about the gene and the disease. The quoted sentences say what the papers report.
osteoporosis (2 papers, 2021 to 2022). A condition of reduced bone mass, with decreased cortical thickness and a decrease in the number and size of the trabeculae of cancellous bone (but normal chemical composition), resulting in increased fracture incidence. "In the last years, numerous studies have shown that altered levels of TBCA expression are associated with human diseases like cancer, neurodegenerative diseases, osteoporosis, and Ankylosing spondylitis." (PMID 33968934, 2021).
clear cell renal cell carcinoma (1 paper, 2021). "TBCA has been found to regulate progression, invasion, and metastasis of clear cell renal cell carcinoma." (PMID 34557456, 2021).
dementia (1 paper, 2026). Loss of intellectual abilities interfering with an individual's social and occupational functions. "SASP scores, even with few proteins, are useful dementia biomarkers, and TBCA is a promising therapeutic target." (PMID 41928789, 2026).
diabetes (1 paper, 2023). "Of the top 15 genes presenting differential methylation in both phenotypes, MAD1L1, TUBB, HIST1H2AL and TBCA were significantly associated with diabetes-related phenotypes in the UK Biobank." (PMID 37239390, 2023).
cancer (4 papers, 2020 to 2024). A tumor composed of atypical neoplastic, often pleomorphic cells that invade other tissues. "Expression of TBCA, COMMD7, LSM4, and FKBP1A were significantly lower in the cancer tissues than the normal tissues." (PMID 39012280, 2024). "As two independent studies have reported a role for these chaperones in the sensitivity/resistance to treatment of different types of cancer, the similarity of S100A4 and TBCA profiles in rat spleen in the context of MM progression is intriguing." (PMID 32290283, 2020). "In addition, we also observed that genes contributing to cancer cell stemness, such as CDKN3, BRIX1, TBCA, TMX2, and others, were highly expressed in the Luminal A DAB2IP-low tumors compared with the DAB2IP-high Luminal A tumors." (PMID 39418101, 2024).
TBCA also shares sentences with these, for which no sentence is quoted: tumor (2 papers); Alzheimer disease (1); ankylosing spondylitis (1); autoimmune disease (1); brain disease (1); breast carcinoma (1); glioma (1); hypoparathyroidism-retardation-dysmorphism syndrome (1); infection (1); neurodegenerative disease (1); non-small cell lung carcinoma (1); schizophrenia (1); thyroid (1).